SLC2A3 (solute carrier family 2 member 3)
Diseases named in the same sentence as SLC2A3 in open-access papers (continued):
Sharing a sentence is not in itself a finding about the gene and the disease.
Hypoglycemia (20 papers, 2010 to 2025). A decreased concentration of glucose in the blood. "Thus, during the first half of gestation, a deficiency in SLC2A3 results in fetal hypoglycemia, reduced fetal development, and altered metabolic hormone concentrations." (PMID 36293384, 2022). "Many interconnected pathways contributing to pancreatic function and glucose metabolism were affected by SLC2A3-RNAi, demonstrating a multifaceted and broad impact of hypoglycemia on the fetal pancreas that is challenging to interpret." (PMID 38731997, 2024). "The true impact of the altered fetal pancreas transcriptome at mid-gestation, as the result of SLC2A3-RNAi-induced fetal hypoglycemia, awaits thorough physiological assessment later in gestation or postnatally." (PMID 38731997, 2024). "Fetal hypoglycemia during the first half of gestation, generated by placenta-specific SLC2A3-RNAi, altered the fetal pancreas transcriptome in multiple aspects." (PMID 38731997, 2024). "The fact that both insulin and glucagon concentrations were reduced suggests that the fetal hypoglycemia induced by SLC2A3 RNAi during the first half of gestation had an overall effect on pancreas development and growth, rather than a β cell-specific effect." (PMID 36293384, 2022). "There were impacts of SLC2A3 RNAi on fetal growth, which may have resulted solely from the hypoglycemia." (PMID 36293384, 2022). "Hypoglycemia is known to upregulate SLC2A1 and SLC2A3, optimizing glucose uptake when blood glucose levels are low, further supporting the observed response in the RES treatment." (PMID 41012809, 2025). "Therefore, we conducted a transcriptomic analysis of fetal pancreases from SLC2A3- and NTS-RNAi pregnancies to further investigate how fetal hypoglycemia during the first-half of gestation contributed to impaired pancreatic growth and function." (PMID 38731997, 2024). "When assessed in pre-term or term FGR placentas, there is a lack of down-regulation of either SLC2A1 or SLC2A3, indicating that the fetal hypoglycemia does not stem from a deficit in glucose transport mechanisms." (PMID 36293384, 2022).
lung cancer (20 papers, 2010 to 2026). A malignant neoplasm involving the lung. "We recently reported that SLC2A3 encoding for GLUT3 is induced by ZEB1 during epithelial–mesenchymal transition (EMT) in tumor cells from non‐small cell lung cancer (NSCLC) and HCC." (PMID 28923827, 2017). "Collectively, our findings highlight that targeting SLC2A3-mediated lactate metabolism, either alone or in combination with PD-1 inhibition, is a potential strategy for treating lung cancer bone metastasis." (PMID 41637551, 2026). "Subsequently, we developed Paris saponin VII, a SLC2A3 inhibitor that effectively suppressed bone metastasis in lung cancer bone metastasis mouse models and patient organoids." (PMID 41637551, 2026). "Here, we show that glucose transporter type 3 (SLC2A3) is notably overexpressed by lung cancer bone metastatic cells and tissues, as a facilitator of lung cancer bone metastasis." (PMID 41637551, 2026). "The most relevant GLUTs in cancer include GLUT1 (SLC2A1), GLUT3 (SLC2A3) and GLUT4 (SLC2A4), which are highly expressed in breast, CRC and lung cancers, with a high affinity for glucose and commonly associated with poor prognosis and therapy resistance." (PMID 41154605, 2025). "Notably, either inhibition of SLC2A3 or lactate limitation improved the tumor response and increased the sensitivity of lung cancer bone metastases to PD-1 treatment." (PMID 41637551, 2026). "However, compared to the primary tumor, lung cancer metastases have higher levels of SLC2A3 and SLC2A5, highlighting their significance in tumor metastasis." (PMID 36518662, 2022). "Lymphoid-specific helicase can inhibit ferroptosis in lung cancer cells, and LSH knockout decreases SLC2A3 and induces ferroptosis, which implies that SLC2A3 may be involved in inhibiting ferroptosis." (PMID 36313616, 2022). "Neither GLUT-3 nor GLUT-4 is positively stained in normal lung epithelia while lung cancers have elevated levels of SLC2A3 and SLC2A4." (PMID 36518662, 2022).
colon carcinoma (19 papers, 2015 to 2026). "In the Cox regression and Kaplan–Meier method which were applied to test the pertinence of the colon cancer’s biomarkers for the prognosis, only two significant genes were identified among the ceRNA network (SLC2A3, P = 0.029; hsa-miR-125b-5p, P = 0.022)." (PMID 32850813, 2020). "High CAV1 expression in advanced colon cancer increased glucose uptake and ATP production by stimulating transcription of glucose transporter 3 (GLUT3, encoded by SLC2A3)." (PMID 27852311, 2016). "This NK signature consists of SLC2A3 and POU2F2, can predict both the prognosis of colon cancer patients and the efficacy of immunotherapy." (PMID 38561388, 2024). "Immunohistochemical methods were used to compare the expression of PRGs (SLC2A3, TMPRSS11E, and UPK3b) in colon cancer and their expression in normal gastric tissues." (PMID 36246625, 2022). "In addition, this group comprises the classical glucose transporters SLC2A3 (GLUT3) which were found to mediate elevated glycolysis in colon cancer cells and SLC2A14 (Glut14) which is a duplication of GLUT3 and is known to be specifically expressed in testis." (PMID 31560702, 2019). "In a recent study, functional analysis revealed a negative correlation between three genes (SLC2A3, TMPRSS11E, and UPK3B) can predict the overall survival of patients with colon cancer, finding that it is negatively correlated with the proliferation and migration of colon cancer cells." (PMID 39062587, 2024).
diabetes (19 papers, 2010 to 2025). "CAMK1, GLUT1/SLC2A1 and GLUT3/SLC2A3 genes were involved in glucose and insulin metabolism that played vital role in development of obesity and diabetes." (PMID 29876008, 2018). "In human pregnancies with pre-existing diabetes, reduction of SLC2A3/GLUT3 expression towards the term was seen." (PMID 31774824, 2019). "SLC2A1 (GLUT1) and SLC2A3 (GLUT3) genes were involved in glucose and insulin metabolism which played vital role in development of obesity, diabetes and CRC." (PMID 29876008, 2018). "HK3, FCN1,CAMK1, GLUT1/SLC2A1 and GLUT3/SLC2A3 are involved in glucose and insulin metabolism that played vital role in development of obesity and diabetes." (PMID 29876008, 2018). "Differentially regulated genes not overlapping with ERCB data also reflected diabetes-associated changes, such as extracellular matrix (ANGPTL4, TNN, DPT, COL9A2) or gestational diabetes (LAT2, HP, CXCL10, CD86, CD68, REN, SLC2A3, VCAM1)." (PMID 33923831, 2021). "However, comparable levels of PECAM1, CXCR2, SLC2A3, BST2, S100A11, S100A12, and CPNE3 were found in neutrophils from diabetes patients and controls (P > 0.05)." (PMID 32377527, 2020). "Alterations of expression levels by diet were observed for all Slc2as/Gluts; greater than two-fold were only observed for Slc2a3/Glut3 at E12.5, for Slc2a6/Glut6 at E9.5 and E18.5, for Slc2a8/Glut8 at E9.5, E12.5 and E18.5, and for Slc2a13/Glut13 at E9.5, regardless of diabetes exposure." (PMID 31774824, 2019).
melanoma (18 papers, 2008 to 2025). A malignant, usually aggressive tumor composed of atypical, neoplastic melanocytes. "For instance, melanoma cells upregulate the gene expression of glucose transporter isoform 1 and 3 (GLUT1/SLC2A1 and GLUT3/SLC2A3) to take up a high amount of glucose." (PMID 35565278, 2022).
Alzheimer disease (14 papers, 2014 to 2026). A progressive, neurodegenerative disease characterized by loss of function and death of nerve cells in several areas of the brain leading to loss of cognitive function such as memory and language. "SLC2A3 plays a key role in glucose metabolism and neuronal function, and GLUT3 expression changes are associated with aging-related neurodegenerative diseases, including Alzheimer’s disease." (PMID 40128656, 2025).
bladder cancer (14 papers, 2012 to 2025). "In bladder cancer, SLC2A3 functions as a risk stratification biomarker and shows strong associations with prognosis, immune landscape, and therapeutic response." (PMID 41268544, 2025). "Moreover, a study of human bladder cancer T24 cells reported that miR-195-5p directly targeted the 3′-untranslated region of GLUT3 and downregulated GLUT3 (protein encoded by SLC2A3) expression to decrease glucose uptake, inhibit cell growth, and promote cell apoptosis." (PMID 35957685, 2022). "Next, m6A RIP-qPCR showed that SLC2A3 was enriched by IP with anti-m6A antibodies in bladder cancer cells." (PMID 37258572, 2023). "Similarly, in bladder cancer, SLC2A3 supports stemness maintenance and tumor progression by meeting the metabolic demands of cancer cells." (PMID 41268544, 2025). "It was found that regulators of cell cycle and cell proliferation such as S100A4, CCND2, C13ORF15 (RGCC), and SYK and genes associated with glucose or ion transport such as SLC2A3 and TMEM16A (ANO1) were upregulated in the persistently infected bladder cancer cells." (PMID 34044804, 2021).
Insulin resistance (14 papers, 2019 to 2025). Increased resistance towards insulin, that is, diminished effectiveness of insulin in reducing blood glucose levels. "Specifically, there were quantitative differences between the expressions of IRS1, PIK3R1, SLC2A1, SLC2A3, and SLC2A4 among the patients with GDM during pregnancy and at 1-year postpartum, i.e., in the two studied groups differing in the degree of insulin resistance." (PMID 39684804, 2024).
non-small cell lung carcinoma (14 papers, 2014 to 2025). A group of at least three distinct histological types of lung cancer, including non-small cell squamous cell carcinoma, adenocarcinoma, and large cell carcinoma. "Previous research has also indicated that elevated expression of SLC2A3, observed in both colorectal and non-small cell lung cancer, acts as a promoter of tumor development." (PMID 38778609, 2025).
thyroid cancer (11 papers, 2019 to 2025). "For instance, HIF-1α can increase GLUT1 and GLUT3 expression, increase the uptake of glucose by thyroid cancer cells, and provide substrates for glycolysis to meet their energy needs through SLC2A1 (encoding GLUT1) and SLC2A3 (encoding GLUT3)." (PMID 40917751, 2025). "Although one study reported a close correlation between the expression of SLC2A1/SLC2A3 mRNA and that of GLUT1/GLUT3 proteins in thyroid carcinoma, further studies are needed to investigate whether the expression of SLC2A mRNA correlates with expression of GLUT protein mRNA in CRC." (PMID 30943948, 2019).
intrauterine growth restriction (10 papers, 2014 to 2025). "Similarly, Slc2a3 mRNA levels have been previous shown to be specifically upregulated in female placentas in a murine lipopolysaccharide-induced intrauterine growth restriction model." (PMID 41258474, 2025). "Due to its abundance and distribution, SLC2A1 is considered the primary glucose transporter within the placenta, but is supported by SLC2A3, which has a higher affinity and transport capacity, at least during the first half of gestation or in some cases of intrauterine growth restriction." (PMID 38474355, 2024). "Fetal hypoglycemia is a hallmark of fetal growth restriction (FGR), and as such, any deficiency in SLC2A3 could impact trophoblast glucose uptake and transfer to the fetus, thus potentially setting the stage for FGR." (PMID 36293384, 2022).
oral squamous cell carcinoma (10 papers, 2010 to 2024). "In oral squamous cell carcinoma, positive cell membrane SLC2A3 protein expression was associated with advanced clinic-staging of tumors and positive expression of SLC2A3 was also associated with unfavorable free-disease survival." (PMID 24124917, 2013). "In this study, we identified the regulatory axis of SLC2A3/LA/TGF-β/SMAD in oral squamous cell carcinoma (OSCC)." (PMID 38625978, 2024). "The GLUT1 (gene: SLC2A1) and GLUT3 (gene: SLC2A3) proteins are significant indicators of a poor prognosis outcome in oral squamous cell carcinoma, probably because of the enhanced glycolytic metabolism of more aggressive neoplastic cells." (PMID 29228563, 2017). "We also found that oral squamous cell carcinoma cells had increased proliferation, migration, invasion, EMT phenotype, and glycolysis due to SLC2A3 overexpression." (PMID 38625978, 2024).
ischemia (9 papers, 2011 to 2025). A hypoperfusion of the BLOOD through an organ or tissue caused by a PATHOLOGIC CONSTRICTION or obstruction of its BLOOD VESSELS, or an absence of BLOOD CIRCULATION. "Though no direct links prove SLC2A3's role in AMI prognosis, GLUT overexpression has been observed alongside improved outcomes in murine ischemia models." (PMID 40672380, 2025).
head and neck squamous cell carcinoma (8 papers, 2010 to 2025). A squamous cell carcinoma that arises from any of the following anatomic sites: lip and oral cavity, nasal cavity, paranasal sinuses, pharynx, larynx, and salivary glands. "For instance, high levels of SLC2A3 were associated with unfavorable outcomes in CRC, gastric (GC), and head and neck squamous cell carcinoma (HNSCC)." (PMID 36497462, 2022).
prostate carcinoma (8 papers, 2019 to 2022). A carcinoma that arises from epithelial cells of the prostate gland. "In prostate cancer, SLC2A3 was one of the high-risk genes, and the risk score was significantly related to NK cell infiltration." (PMID 36247875, 2022). "For instance, miR-29c inhibited cell growth and glucose metabolism in prostate cancer by targeting SLC2A3." (PMID 36497462, 2022). "In prostate cancer, SLC2A3 was a direct target of miR-29c to inhibit cell growth and glucose metabolism." (PMID 36247875, 2022). "Furthermore, highly expressed miR-29c can inhibit prostate cancer cell proliferation by inhibiting SLC2A3 expression." (PMID 33173535, 2020). "In prostate cancer, a few regulators, such as HK2 and SLC2A3, were indicated to participate in the regulation of PCa progression." (PMID 35242214, 2022).
leukemia (7 papers, 2019 to 2025). A malignant (clonal) hematologic disorder, involving hematopoietic stem cells and characterized by the presence of primitive or atypical myeloid or lymphoid cells in the bone marrow and the blood. "SLC2A3 expression levels were found to be increased in virtually all types of cancer cell lines, including leukemia." (PMID 32429253, 2020). "We used seven patient-derived primary leukaemia cells to confirm the role of SLC2A3 in vitamin C treatment." (PMID 32203209, 2020). "We noted a consistent upregulation of glucose importers SLC2A1 and SLC2A3 in leukemic cells, but also various other glycolysis-related genes were upregulated in leukemia although variation between different cell lines was noted as well." (PMID 31890203, 2019). "Liu and their colleagues demonstrated that the SLC2A3 could lead to the reduction of vitamin C uptake, therefore inhibiting leukemia development." (PMID 37063301, 2023). "Liu and collaborators recently showed a lower expression of the SLC2A3 gene (GLUT3), but not of the SLC2A1 gene (GLUT1), in leukemia blasts compared with normal hematopoietic cells." (PMID 33804775, 2021).
Cerebral ischemia (6 papers, 2015 to 2024). Restriction of arterial blood supply to the brain associated with insufficient oxygenation to support the metabolic requirements of the tissue. "SLC2A3 also known as GLUT3, is significantly up-regulated in the penumbra after cerebral ischemia." (PMID 38154101, 2023).
head and neck carcinoma (6 papers, 2010 to 2025). A carcinoma that arises from the head and neck region. "Therefore, further experimental validation should be conducted to clarify the mechanism of the effect of SLC2A3 on immune cells and the development of head and neck carcinoma." (PMID 38778609, 2025).
lymph node metastasis (6 papers, 2010 to 2024). "High SLC2A3 expression also indicates the susceptibility of lymph node metastasis, distant metastasis, and MSI-H." (PMID 34211835, 2021). "Also, bioinformatics analyses by Chu predict that upregulated SLC2A3 may link to advanced clinical stages and lymph node metastasis." (PMID 38625978, 2024).
lymphoma (6 papers, 2015 to 2022). A malignant (clonal) proliferation of B- lymphocytes or T- lymphocytes which involves the lymph nodes, bone marrow and/or extranodal sites. "Low SLC2A3 expression was associated with less effective demethylation, and a diminished vitamin C effect in the AML and lymphoma cell lines." (PMID 32203209, 2020). "In acute myeloid leukemia (AML), a SLC2A3-knockdown cell line accounted for the less effective demethylation and vitamin C in the AML and lymphoma cell lines suggesting SLC2A3 could act as a predictive biomarker in vitamin C treatment in AML." (PMID 36247875, 2022).
clear cell renal cell carcinoma (5 papers, 2020 to 2023). "For example, LINC01094 was found to upregulate SLC2A3 by targeting microRNA-184, subsequently promoting the development of clear cell renal cell carcinoma." (PMID 35568824, 2022). "Furthermore, NICI expression is regulated by the von Hippel–Lindau (VHL) tumor suppressor and is highly expressed in clear cell renal cell carcinoma (ccRCC), where SLC2A3 expression is associated with patient prognosis, implying an important role for the HIF/NICI/SLC2A3 axis in this malignancy." (PMID 31690629, 2020).
laryngeal carcinoma (5 papers, 2015 to 2025). Carcinoma that arises from the laryngeal epithelium. "Since SLC2A3 or GLUT3 genes are associated with prognosis in CRC as well as thyroid or laryngeal carcinoma, it would be worthwhile to investigate whether these cancers have similar GLUT-dependent metabolic pathways." (PMID 30943948, 2019). "A positive expression of SLC2A1 and SLC2A3 transcripts was confirmed in 83.9 % (89/106) and 82.1 % (87/106) samples of laryngeal cancer, respectively." (PMID 25412955, 2015). "A significant difference was noted in the levels of GLUT1 and GLUT3 mRNA in laryngeal cancer tissue compared to adjacent normal laryngeal tissue (p < 0.001 and p < 0.001, for the SLC2A1 and SLC2A3 genes, respectively)." (PMID 25412955, 2015). "In conclusion, our findings suggest that both the SLC2A1 and SLC2A3 genes, as well as the related GLUT1 and GLUT3 proteins, can affect the behavior of laryngeal cancer." (PMID 25412955, 2015). "Positive expression of SLC2A1, SLC2A3, and HIF-1α genes was noted in 83.9, 82.1, and 71.7 % of SCC specimens and in 34.4, 59.4, and 62.5 % of laryngeal cancer samples." (PMID 25412955, 2015). "Since copies of the studied genes were found in only 2 % cases of laryngeal carcinoma, it can be concluded that SLC2A1 and SLC2A3 amplification does not affect the expression of GLUT1 and GLUT3 in this type of neoplasm." (PMID 25412955, 2015).
lung squamous cell carcinoma (5 papers, 2022 to 2024). "The best studied glucose transporters and hexokinase enzymes in cancer, including in squamous cell lung cancer, are GLUT1, SLC2A3 (also known as Glucose Transporter 3 or GLUT3), Hexokinase 1, and Hexokinase 226,27." (PMID 36697489, 2023). "High expression of SLC2A3, also known as glucose transporter 3(GLUT3), portends a poor prognosis of the patients with most cancer types including lung squamous cell carcinoma." (PMID 36131791, 2022).